EGFR (epidermal growth factor receptor)
Diseases named in the same sentence as EGFR in open-access papers (continued):
Sharing a sentence is not in itself a finding about the gene and the disease.
lung adenocarcinoma (continued). "The present findings can produce a predictive scoring system that lets physicians acquire an exhaustive report on managing the therapeutic strategy for EGFR-mutated lung adenocarcinoma." (PMID 35330404, 2022). "Meanwhile, the types of TCM syndromes under EGFR mutations in lung adenocarcinoma are dominated by Qi and Yin deficiency syndrome, and treatment should pay attention to tonifying Qi and nourishing Yin." (PMID 35431966, 2022). "Lung adenocarcinoma patients with an initial mutation in the EGFR gene (n = 20) were enrolled for follow-up with ctDNA liquid biopsies (n = 37)." (PMID 36497340, 2022). "In this paper, we retrospectively analyzed two cases of lung adenocarcinoma with L718Q/V mutations of EGFR exon 18 through next generation sequencing (NGS) technique." (PMID 35943592, 2022). "Here, we will report an EGFR-mutated lung adenocarcinoma patient with heterogeneity of resistant mechanisms including EGFR amplification, large fragment deletion of RB1, and histological transformations after targeted treatments." (PMID 36033496, 2022). "In total, 728 patients with lung adenocarcinoma were included, and divided into three groups according to EGFR mutation subtypes." (PMID 35574401, 2022). "divided lung adenocarcinoma into three subtypes by unsupervised clustering analysis, and found that patients with EGFR mutations had shorter disease-free survival times." (PMID 36159794, 2022). "Mutations in ALK and EGFR have caused huge changes in the treatment of patients with lung adenocarcinoma." (PMID 35463955, 2022). "Epidermal growth factor receptor (EGFR) mutations remains the most common driver mutations in patients with lung adenocarcinomas (LUAD), with an incidence of 50% in Asians and 9.8% in Caucasian Europeans." (PMID 35296087, 2022). "Knowing that L-score was negatively correlated with EGFR amplification status in lung adenocarcinoma, we then examined the association between L-score and lung adenocarcinoma cell line sensitivity to EGFR inhibitors." (PMID 35016696, 2022). "In tumor cells of lung adenocarcinoma with EGFR mutations, primary EGFR-TKI resistance was associated with high hepatocyte growth factor in CAFs." (PMID 35326670, 2022). "There is a positive relationship between tumor PD-L1 expression and EGFR mutation status and poor prognosis in lung adenocarcinoma." (PMID 35222387, 2022). "Our group has previously reported on the mechanisms by which tumors acquire resistance against third-generation EGFR-TKIs (osimertinib and rociletinib) using afatinib-resistant lung adenocarcinoma PC-9 cells harboring an acquired T790M mutation in EGFR." (PMID 35883645, 2022). "Early onset LM predicted a significantly worse outcome in EGFR-mutant lung adenocarcinoma patients and radiological severity predicted higher tumor cell counts if CSF and a higher detection rate of EGFR mutation in CSF." (PMID 35740489, 2022). "We also discussed the possibility for the future application of alectinib as an ALK-TKI for lung adenocarcinoma patients having an EGFR mutation and an ALK rearrangement (double positive)." (PMID 36107507, 2022). "Thoracic radiotherapy plays an increasingly important role in the stage IV lung adenocarcinomas (oligo-metastasis), harboring EGFR mutations." (PMID 36153486, 2022). "Intense expression of EGFR exon 19 del characterizes lung adenocarcinoma in patients with NP-MCP and it’s a potential risk factor for OLNM." (PMID 35912197, 2022). "MMP1 has been already reported to cause resistance of lung adenocarcinoma to EGFR-TKIs through mTOR pathways." (PMID 35480306, 2022). "The upregulation of the EGFR signaling pathway is associated with many cancers, including glioblastoma, lung adenocarcinoma, and endometrial carcinoma." (PMID 35178099, 2022). "In a clinical trial (NCT00525148), afatinib demonstrated activity in the treatment of patients with advanced lung adenocarcinoma with EGFR mutations, especially in patients harboring deletion 19 or L858R mutations." (PMID 36591517, 2022).
lung adenocarcinoma (continued). "The current study assessed the frequency and types of mutations in epidermal growth factor receptor (EGFR) genes in patients with lung adenocarcinoma." (PMID 35463723, 2022). "For example, it can be applied in the prediction of the epidermal growth factor receptor mutation status in lung adenocarcinoma and MYCN amplification in neuroblastoma." (PMID 35204353, 2022). "The phase III CONVINCE trial aimed to assess the efficacy and safety of first-line icotinib versus chemotherapy in lung adenocarcinoma patients with exon 19/21 EGFR mutations." (PMID 36482474, 2022). "A correlation between EGFR expression and genes associated with cholinergic muscarinic receptors was observed in lung adenocarcinoma and lung squamous cell carcinoma." (PMID 35565451, 2022). "Our study provides insight into how exosomes promote invasion and hybrid EMT in EGFR-mutated lung adenocarcinoma, most likely through the PI3K/AKT/mTOR pathway." (PMID 35954442, 2022). "In this study, a total of 517 EGFR-mutated lung adenocarcinoma patients with ECOG-PS ≥ 2 who were treated with either gefitinib, erlotinib, or afatinib as first-line systemic treatments were included." (PMID 35158940, 2022). "Here, we found that high expression of SIRT6 is associated with poor prognosis of lung adenocarcinoma, especially in EGFR-mutated NSCLC patients." (PMID 35915188, 2022). "Mutated KRAS and EGFR are common oncogenic drivers of lung adenocarcinoma with predictive value for targeted therapies." (PMID 35627184, 2022). "We herein report an EGFR T790M mutation positive lung adenocarcinoma that showed histologic transformation to SQ after erlotinib treatment; thus demonstrating the efficacy of osimertinib." (PMID 35960133, 2022). "For patients with EGFR-mutated lung adenocarcinoma who used EGFR-TKIs as frontline therapy, liberal brain MRI follow-up showed more advantages in terms of cost." (PMID 36457515, 2022). "Cases of advanced lung adenocarcinoma with EGFR mutation combined with concomitant non-EGFR genetic alterations were retrospectively collected." (PMID 36172729, 2022). "EGFR mutations are the most important drivers of gene alterations in lung adenocarcinomas and are sensitive to EGFR-TKIs." (PMID 36033496, 2022). "Combined treatment of gefitinib with MEK inhibitors was shown to be therapeutically useful in lung adenocarcinoma cells with acquired gefitinib resistance and EGFR mutations." (PMID 35625872, 2022). "A personalized therapeutic strategy is urgently needed to improve the survival outcomes in patients with advanced EGFR-mutated lung adenocarcinoma." (PMID 35053473, 2022). "CLEC11A expression was also frequently elevated in lung adenocarcinoma (LAC) tissues with EGFR mutation." (PMID 35267664, 2022). "In lung adenocarcinomas bearing EGFR mutations, primary EGFR-TKI resistance is mediated via hepatocyte growth factor from CAFs." (PMID 35326670, 2022). "Patients with lung adenocarcinoma and EGFR mutation have a response rate of up to 81.6% and a PFS of approximately 9.7 to 13.3 months." (PMID 35209919, 2022). "We aimed to develop, validate, and evaluate the clinical utility of a deep learning model for predicting EGFR mutation status in lung adenocarcinoma manifesting as pGGN on computed tomography (CT)." (PMID 36119545, 2022). "The association between sarcopenia and treatment-related toxicity and survival in patients with lung adenocarcinoma and EGFR mutations needs further research." (PMID 35330404, 2022). "Two cases of stage IV lung adenocarcinoma with EGFR mutation were reported and the disease was controlled after EGFR-TKIs treatment." (PMID 36419397, 2022). "For EGFR-positive lung adenocarcinoma patients, exon 21 L858R mutation showed a maximum propensity towards metastasis, hence poor prognosis." (PMID 36613084, 2022). "It is a protective predictor of overall survival in patients with stage IV EGFR-mutated lung adenocarcinoma treated with TKIs." (PMID 35387120, 2022).
lung adenocarcinoma (continued). "Mutations that cause EGFR upregulation are associated with cancer, with EGFR mutations present in 12-38% of lung adenocarcinomas, the main form of non-small cell lung cancer (NSCLC)." (PMID 36203432, 2022). "We retrospectively analyzed patients with stage IV lung adenocarcinoma to evaluate the prevalence of the EGFR Q787Q polymorphism and its influence on effects of tyrosine kinase inhibitor (TKI) treatment." (PMID 35387120, 2022). "The frequency of EGFR mutation in lung adenocarcinoma patients referred to a specialized lung disease hospital has been investigated." (PMID 35463723, 2022). "Epidermal growth factor receptor (EGFR) mutations in lung adenocarcinoma predict benefit with tyrosine kinase inhibitors (TKIs)." (PMID 35433405, 2022). "At this point, the study focused on the detection of genetic mutations involved in treatment resistance, specifically the EGFR-T790M mutation in lung adenocarcinoma." (PMID 36497340, 2022). "At the time of diagnosis, all nine patients had a histologically-confirmed diagnosis of lung adenocarcinoma and an EGFR mutation." (PMID 35268520, 2022). "Previous studies suggested that the micropapillary component as a histological subtype appeared to be associated with postoperative recurrence in patients with EGFR-mutated lung adenocarcinoma." (PMID 34652430, 2022). "Patients being treated with 40 mg afatinib were significantly younger than other patients, suggesting that physicians prefer the use of TKIs for EGFR-mutated lung adenocarcinoma patients." (PMID 35158940, 2022). "It is highly expressed in lung adenocarcinoma, especially in those with EGFR mutations, and is considered to be a biomarker for prognosis." (PMID 35204661, 2022). "The current research provided novel evidence of the clinical prescription of frontline EGFR-TKIs for EGFR-mutated lung adenocarcinoma patients with a PS score ≥2." (PMID 35158940, 2022). "EGFR overexpression and high gene copy numbers have been associated with tumor progression in lung adenocarcinoma treated with EGFR inhibitors." (PMID 35978803, 2022). "Positive EGFR mutation is still a protective factor in PFS for lung adenocarcinoma patients with pleural effusion (HR 0.69; 95% CI 0.54–0.89)." (PMID 35209915, 2022). "For example, in a study including lung adenocarcinoma with pleural metastasis, epidermal growth factor receptor (EGFR) mutation status was discordant between primary tumors and corresponding pleural metastases in 16% of patients." (PMID 35454064, 2022). "In a different, more thorough investigation, 20 patients with lung adenocarcinoma had their EGFR mutations and T790M mutations molecularly tested using cfDNA from BALF." (PMID 36552956, 2022). "EGFR signaling regulates global metabolic pathways in EGFR-mutated lung adenocarcinoma and EGFR-TKIs such as erlotinib and gefitinib are reported to drive energetic stress thus activate the AMPK pathway in EGFR (del19) lung tumors." (PMID 37192859, 2022). "We conduct the present study in order to evaluate the association between clinical presentations, brain images, tumor cell counting of CSF, and EGFR mutation detection rates among EGFR-mutant lung adenocarcinoma patients with LM." (PMID 35740489, 2022). "Most of the EGFR mutations were from lung adenocarcinoma, at about 68%, and malignant melanoma, approximately 5%." (PMID 35627184, 2022). "The present study investigated the combination of systemic inflammation and tumor heterogeneity biomarkers in predicting survival outcomes in patients with advanced EGFR-mutated lung adenocarcinoma treated with a first-line TKI." (PMID 35053473, 2022). "Here we reported 2 patients with advanced EGFR mutated lung adenocarcinomas treated with the first-generation TKI and the subsequent osimertinib." (PMID 33725888, 2021).
lung adenocarcinoma (continued). "These drugs have been employed in clinical use as first/second treatment line for EGFR-mutated lung adenocarcinoma patients leading to response rates and progression-free survival (PFS) ranging from 56% to 83% and 8.4‒18.9 months." (PMID 33806258, 2021). "Our experience suggests that the use of tyrosine kinase inhibitors (TKIs) as front-line treatment is a more reasonable and safe option for EGFR-mutated lung adenocarcinoma, with ICIs considered as a possible further treatment in sequential approaches." (PMID 34456717, 2021). "For example, the lung adenocarcinoma cell line NCI-H1975 harbours both the primary activating L858R mutation that increases the affinity for the EGFR inhibitor gefitinib and the secondary T790M mutation that imparts resistance to gefitinib." (PMID 34610265, 2021). "The data obtained confirmed the presence of the characteristic EGFR mutation in the lung adenocarcinoma cell lines HCC4006 and HCC827." (PMID 34966671, 2021). "This study was conducted with the latest population-based RWD to evaluate relative survival rate and TTF of first-line treatment for EGFR-mutated advanced lung adenocarcinoma in Taiwan." (PMID 34434112, 2021). "The most common current therapeutic target in lung adenocarcinoma (ADC) consists of epidermal growth factor receptor (EGFR) mutations." (PMID 33869038, 2021). "Lung adenocarcinomas (LUADs) harbouring epidermal growth factor receptor (EGFR) mutations are generally unable to benefit from immune checkpoint inhibitors (ICIs) due to an immunosuppressive tumour microenvironment (TME) and a lower tumour mutation burden." (PMID 34631565, 2021). "Management of transformed SCLC from EGFR-mutated lung adenocarcinoma is based on use of chemotherapy including etoposide/carboplatin and taxanes, which results in a median OS of 10.9 months." (PMID 34202748, 2021). "Variations within the histological type have also been observed for bone affinity; for example, Epidermal Growth Factor Receptor (EGFR)-mutated lung adenocarcinoma have a higher bone affinity than the one with ALK translocation." (PMID 34830865, 2021). "The second case was of a 57-year-old man with stage IV (cT3N3M1b) lung adenocarcinoma with exon 21 L861Q EGFR mutation." (PMID 34721009, 2021). "Global DNA methylation landscape of tumors from patients with lung adenocarcinoma before TKI treatment was analyzed to investigate the association with EGFR-TKI responses." (PMID 34036228, 2021). "We characterized an association between pleural angiogenesis and endothelial EGFR expression from lung adenocarcinoma patients with MAPF; it also presented in the pleural tissue of squamous cell carcinoma." (PMID 34680445, 2021). "In this study, we first used the TCGA lung adenocarcinoma database to recognize the correlation between EGFR and ERK expression and evaluated the association between ERK and Osimertinib resistance in tissue pairs." (PMID 34885115, 2021). "In this study, we developed a stacking model based on SE-ResNet using non-invasive 18F-FDG PET/CT images to predict EGFR mutation status for patients with lung adenocarcinoma." (PMID 34367993, 2021). "In pleural tissues of EGFR-mutated lung adenocarcinoma, histology revealed microvessel formation similar to that previously reported." (PMID 34680445, 2021). "Phenotypic histological transformation to SCLC represents another major resistance mechanism in EGFR-mutated lung adenocarcinoma." (PMID 34202748, 2021). "Among these is osimertinib, which has a high affinity for binding to the ATP pocket in the kinase domain of EGFR and, correspondingly, has excellent activity against T790M-mutated lung adenocarcinoma." (PMID 34202748, 2021). "In this study, the effects of CDDP in lung adenocarcinoma cell lines containing different clinically relevant mutations, including EGFR mutations, were examined." (PMID 34966671, 2021).
lung adenocarcinoma (continued). "Our study contributes to a comprehensive view of the evolution of the tumor genome during the treatment of EGFR-mutated lung adenocarcinoma patients." (PMID 33919291, 2021). "Epidermal growth factor receptor (EGFR) gene‐activating mutations are the primary oncogenic drivers in lung adenocarcinoma." (PMID 33528892, 2021). "A limited number of case reports have indicated that lung adenocarcinoma patients with an EGFR-L747P mutation have different sensitivities depending on the type of EGFR-TKI13–19." (PMID 33863983, 2021). "Here, we reported an advanced lung adenocarcinoma case concurrent with EGFR sensitive mutation and high PD-L1 expression (>50%) that was administrated with gefitinib firstly, and then became resistant to EGFR-TKI." (PMID 34249697, 2021). "A 48-year-old woman was diagnosed with stage IV lung adenocarcinoma harboring the EGFR mutation in the combination of chest computed tomography, biopsy and amplification refractory mutation system-polymerase chain." (PMID 34871271, 2021). "The frequencies of EGER 19Del mutations and EGFR wild type were significantly different with lung adenocarcinoma with predominant ground -glass opacity." (PMID 34804960, 2021). "Case presentation: The first case was of a 58-year-old male with advanced lung adenocarcinoma (cT4bN3M1b) with exon 18 G719X and exon 20 S781I EGFR mutations and received afatinib therapy." (PMID 34721009, 2021). "In this study, we investigated the risk factors of acquired T790M mutation among patients with lung adenocarcinoma with epidermal growth factor receptor (EGFR) tyrosine mutation who were treated with EGFR‐tyrosine kinase inhibitors (TKIs)." (PMID 33529490, 2021). "In conclusion, a lower starting dose (30 mg daily) of afatinib for patients of lung adenocarcinoma harboring susceptible EGFR mutations showed similar RR, PFS, and OS compared with those receiving a standard 40 mg daily as the initial dose of afatinib." (PMID 33941115, 2021). "EGFR mutations are major driving genetic alterations that account for 15–50% of patients diagnosed with lung adenocarcinoma." (PMID 34956890, 2021). "Here, we described a patient with biphasic mesothelioma of the pleura showing rare morphology mimicking the myxofibrosarcoma concomitant with EGFR-mutated lung adenocarcinoma." (PMID 34333253, 2021). "We investigated the clinical outcomes of afatinib, erlotinib, and gefitinib according to EGFR mutation type in patients with lung adenocarcinoma." (PMID 33430803, 2021). "Epidermal growth factor receptor (EGFR) mutations have been identified in approximately 50% of Asian and 10–15% of Caucasian lung adenocarcinoma patients." (PMID 34961817, 2021). "The present results indicate that WWOX rs3764340 SNP is associated with a significantly increased risk of lymph node involvement in patients with lung adenocarcinoma carrying EGFR mutations." (PMID 34948746, 2021). "We investigated resected EGFR-mutated lung adenocarcinoma mutation profiles to evaluate prognostic impacts." (PMID 34298845, 2021). "The phase-2 AURA2 trial assessing the safety and efficacy of osimertinib in TKI-pretreated patients with EGFR-mutated lung adenocarcinoma bearing T790M mutations demonstrated a 70% ORR." (PMID 34202748, 2021). "Three hundred and one lung adenocarcinoma patients with EGFR mutation status were enrolled in this study." (PMID 34367993, 2021). "A total of 34 patients with EGFR‐sensitive mutation‐positive lung adenocarcinoma and acquired resistance to the first generation of epidermal growth factor receptor‐tyrosine kinase inhibitors (EGFR‐TKIs) were enrolled." (PMID 33932095, 2021). "Immune checkpoint inhibitors (ICI) as monotherapy result in disappointing outcomes in patients with EGFR-mutated lung adenocarcinoma, with low responses rates and low survival and should only be considered after exhaustion of other systemic therapies." (PMID 34201833, 2021).